ZIC1 (Zic family zinc finger 1)
Description:
Acts as a transcriptional activator. Involved in neurogenesis. Plays important roles in the early stage of organogenesis of the CNS, as well as during dorsal spinal cord development and maturation of the cerebellum. Involved in the spatial distribution of mossy fiber (MF) neurons within the pontine gray nucleus (PGN). Plays a role in the regulation of MF axon pathway choice. Promotes MF migration towards ipsilaterally-located cerebellar territories. May have a role in shear flow mechanotransduction in osteocytes. Retains nuclear GLI1 and GLI3 in the cytoplasm. Binds to the minimal GLI-consensus sequence 5'-TGGGTGGTC-3' (By similarity).
Synonyms: ZIC; ZNF201; BAIDCS; CRS6
Tractability: No criterion of Open Targets' tractability assessment is met for any kind of drug.
Gene: Protein-coding gene on chromosome 3 (147,393,422 to 147,510,293, forward strand). Ensembl gene ENSG00000152977.
Subcellular location: Nucleus; Cytoplasm
Subcellular location (Human Protein Atlas): Nucleoplasm
Pathways (Reactome):
Developmental Biology: Specification of the neural plate border; Transcriptional and post-translational regulation of MITF-M expression and activity
Gene Ontology:
Molecular function: protein binding; sequence-specific double-stranded DNA binding; DNA-binding transcription factor activity; DNA-binding transcription factor activity, RNA polymerase II-specific; RNA polymerase II cis-regulatory region sequence-specific DNA binding; DNA-binding transcription activator activity, RNA polymerase II-specific; promoter-enhancer loop anchoring activity; RNA polymerase II transcription regulatory region sequence-specific DNA binding
Biological process: brain development; central nervous system development; inner ear morphogenesis; pattern specification process; positive regulation of DNA-templated transcription; positive regulation of protein import into nucleus; regulation of smoothened signaling pathway; regulation of transcription by RNA polymerase II; forebrain development; gene expression; hippocampus development; maintenance of cell number; olfactory bulb development; positive regulation of transcription by RNA polymerase II; spinal cord development
Cellular component: nucleoplasm; nucleus; cytoplasm
Genetic constraint (gnomAD): Loss-of-function variants: 4 observed, 29.89 expected, observed/expected ratio (o/e) 0.13, 90% interval 0.065 to 0.31. The upper end of that interval is the gene's LOEUF score, 0.31, which puts it in group 1 of 6, group 1 being the genes least tolerant of losing a copy. Missense variants: 441 observed, 641.93 expected, observed/expected ratio (o/e) 0.69, 90% interval 0.63 to 0.74. Synonymous variants: 305 observed, 276.77 expected, observed/expected ratio (o/e) 1.1, 90% interval 1 to 1.21.
Gene-disease validity (ClinGen):
ClinGen rates the evidence that ZIC1 causes each of these diseases.
craniosynostosis 6 (autosomal dominant): Definitive. Any craniosynostosis in which the cause of the disease is a mutation in the ZIC1 gene.
Homologues: Orthologues: chimpanzee ZIC1 (100% identical), macaque ZIC1 (100% identical), dog ZIC1 (99% identical), pig ZIC1 (99% identical), mouse Zic1 (99% identical), rat Zic1 (99% identical), tropical clawed frog zic1 (92% identical), zebrafish zic1 (89% identical). Paralogues in human: ZIC2 (77% identical), ZIC3 (68% identical), ZIC5 (53% identical), ZIC4 (47% identical), GLI2 (35% identical), GLI3 (34% identical), GLIS3 (28% identical), GLI1 (27% identical), GLIS1 (25% identical), GLIS2 (24% identical), ZXDA (23% identical), ZXDB (23% identical), and 2 more.
Diseases named in the same sentence as ZIC1 in open-access papers:
ZIC1 is named in the same sentence as 78 diseases in open-access papers, as found by Europe PMC text mining. Sharing a sentence is not in itself a finding about the gene and the disease. The quoted sentences say what the papers report.
gastric cancer (13 papers, 2011 to 2024). A primary or metastatic malignant neoplasm involving the stomach. "ZIC1 was implicated as a tumor suppressor silenced via promoter methylation in malignant pleural mesothelioma and gastric cancer." (PMID 25472429, 2014). "Literature mining informed us that FOXO1 and EGR1 have been implicated in HCC, and ZIC1 is down-regulated in gastric cancer and has been proved to be a tumor suppressor gene in colorectal cancer." (PMID 24278165, 2013). "Promotor methylation of ZIC1 is associated with gastric cancer." (PMID 27191985, 2016). "However, little is known about the mechanism underlying ZIC1 function in the development and progression of gastric cancer." (PMID 22799764, 2012). "Recently, ZIC1 gene was found to be silenced in colon cancer cell lines, primary colorectal cancer tissues, and gastric cancer." (PMID 33501605, 2021). "Previous studies have shown that ZIC1 is frequently methylated in colorectal, hepatocellular, and gastric cancers while the methylation of ZIC4 was observed in bladder cancer." (PMID 27553089, 2017). "Emerging studies have also shown that tumor suppressor genes (e.g. RNF180, Zic1) are frequently methylated, not only in gastric cancer, but also among patients with pre-malignant gastric lesions." (PMID 29348893, 2017). "Clinicopathological parameters and detection of Zic1 hypermethylation in plasma from gastric cancer (GC) patients." (PMID 26207911, 2015). "ZIC1 expression is downregulated in gastric carcinomas and increased in desmoid tumour fibroblasts and brain tumours (medulloblastomas and meningiomas)." (PMID 24148222, 2013). "We have previously shown that overexpression of ZIC1 can alter G1/S transition in gastric cancer cells." (PMID 22799764, 2012). "To further understand the mechanisms underlying the inhibition of cell proliferation by overexpression of ZIC1, we evaluated cell-cycle distributions in gastric cancer cells." (PMID 22799764, 2012). "ZIC1 suppresses the Shh signaling pathway which is critical for the regulation of cell-cycle distributions and cell migration in gastric cancer." (PMID 22799764, 2012). "The regulation of sonic hedgehog (Shh), phosphoinositide 3-kinase (PI3K) and mitogen-activated protein kinase (MAPK) signaling pathways after ectopic expression of ZIC1 in gastric cancer cells were evaluated." (PMID 22799764, 2012). "In our present study, we demonstrate that overexpression of ZIC1 suppresses gastric cancer cell migration and invasion, as well as alters the cell-cycle distributions." (PMID 22799764, 2012). "Summarily, we propose a model that represents the pathways through which ZIC1 contributes to gastric cancer progression." (PMID 22799764, 2012). "In this regard, the CDK1 inhibitor p21 was activated, while cyclin D1 inactivated, after overexpression of ZIC1 in gastric cancer cells." (PMID 22799764, 2012). "We have previously shown that ZIC1 gene is significantly downregulated in gastric cancer tissues and cell lines when compared with that of normal gastric tissues." (PMID 22799764, 2012). "We also identified multiple important ZIC1 downstream targets in gastric cancer cells by cDNA microarray analysis." (PMID 22799764, 2012). "Overexpression of ZIC1 contributes to the inhibition of cell proliferation migration and cell-cycle distribution in gastric cancer." (PMID 22799764, 2012). "To address this issue, we examined the expression of Sonic hedgehog (Shh), a key member of Hh family, in gastric cancer cells after overexpression of ZIC1." (PMID 22799764, 2012). "Another major finding in our present study is that ZIC1 transcriptionally regulates Sonic hedgehog (Shh) signaling in gastric cancer cells." (PMID 22799764, 2012). "Thus, we have revealed that ZIC1 plays important roles in gastric cancer progression by regulation of the Shh signaling pathway." (PMID 22799764, 2012). "ZIC1 serves as a potential therapeutic target for gastric cancer." (PMID 22799764, 2012).
gastric cancer (continued). "Taken together, our results suggest that ZIC1 may transcriptionally regulate the expression of Shh in gastric cancer cells." (PMID 22799764, 2012). "ZIC1 can transcriptionally downregulate the Shh signaling and suppress the level of phospholated Akt and Erk, thus leads to the regulation of cell-cycle regulator kinases p21Waf1/Cip1, p27Kip1 and cyclin D1 in gastric cancer cells." (PMID 22799764, 2012). "Elucidation of this signaling network may provide further insight into the role of ZIC1 in gastric cancer." (PMID 22799764, 2012). "Though the results need to be validated in future studies, our miroarray data have revealed that other key components of cell cycle kinase regulators including TP53INPI and CDKN2B, are deregulated with forced expression of ZIC1 in an individual MKN28 gastric cancer cell line." (PMID 22799764, 2012). "Moreover, ZIC1 inhibits cell cycle regulatory kinases, p21, p27 and cyclin D1, thus leading to G1/S cell cycle transit in gastric cancer cells." (PMID 22799764, 2012). "We hypothesized that Hh signaling pathway may be involved in the ZIC1 regulation of gastric cancer cell-cycle and cell migration." (PMID 22799764, 2012). "We have identified ZIC1 as a novel candidate TSG in gastric cancer." (PMID 21347233, 2011). "Finally, we have systemically identified ZIC1 downstream targets by cDNA microarray analysis and revealed that 132 genes are down-regulated and 66 genes are up-regulated after transfection with ZIC1 in gastric cancer cells." (PMID 22799764, 2012). "As a zinc finger transcription factor, ZIC1 also potentially modulates the transcriptional expression of target genes by directly binding to GC-rich sequences, thus functioning as a tumour suppressor by inhibition of cell proliferation, cell migration and invasion in gastric cancer." (PMID 22799764, 2012). "In addition, we determined the role of ZIC1 in cell migration and invasion in gastric cancer." (PMID 22799764, 2012). "Nevertheless, the influence of ZIC1 on the Hh signaling pathway in gastric cancer remains unknown." (PMID 22799764, 2012). "To determine the effect of ZIC1 on cell proliferation, we performed cell viability analysis by MTS assays in gastric cancer cells." (PMID 22799764, 2012). "The suppression of cell proliferation by ZIC1 was consistent with our previous observations in AGS and MKN28 gastric cancer cells, as well as colon cancer cells." (PMID 22799764, 2012). "We observed that re-expression of ZIC1 significantly suppressed cell migration in AGS, BGC823 and SGC7901 gastric cancer cell lines (p < 0.001)." (PMID 22799764, 2012). "We have shown that re-expression of ZIC1 effectively inactivate the phosphorylated Akt and Erk1/2 in AGS, MKN28, BGC823 and SGC7901 gastric cancer cell lines." (PMID 22799764, 2012). "Our previous work has revealed that the Zic1 promoter is frequently methylated in primary gastric carcinoma tissues, with a high detection rate of 94.6%, but not in normal gastric tissues." (PMID 26207911, 2015). "To systematically determine downstream targets of ZIC1, we conducted an affymatrix oligonucleotide microarray in MKN28 gastric cancer cells with or without pCDNA3.1-ZIC1." (PMID 22799764, 2012). "Therefore, we propose that ZIC1 regulates G1/S transit mainly through PI3K and MAPK pathways and downstream cell-cycle regulator kinases in gastric cancer cells." (PMID 22799764, 2012). "Overexpression of ZIC1 results in inactivation of Shh, PI3K and MAPK signaling pathways, as well as regulation of multiple downstream targets which are essential for the development and progression of gastric cancer." (PMID 22799764, 2012). "The absent or low expression of ZIC1 mRNA in gastric cancer cells was mainly meditated by promoter DNA methylation." (PMID 22799764, 2012).
craniosynostosis (10 papers, 2015 to 2026). Craniosynostosis is defined as the premature fusion of one or more cranial sutures leading to secondary distortion of skull shape resulting in skull deformities with a variable presentation. "Heterozygous deletions encompassing ZIC1 and ZIC4 cause Dandy-Walker malformation, whilst in the final exon heterozygous ZIC1 variants result in a distinct phenotype of craniosynostosis with variable intellectual disability via a gain-of-function mechanism." (PMID 42028696, 2026). "In assessing the association of ZIC1 mutations with craniosynostosis, two features are particularly striking: the highly localized distribution of the mutations and the severity of the phenotype." (PMID 26340333, 2015). "Gain of function of ZIC1 is associated with craniosynostosis and learning disability." (PMID 39405291, 2024). "Gain-of-function mutations in ZIC1 cause coronal craniosynostosis and learning disability." (PMID 36225206, 2022). "Gain-of-function mutations in ZIC1 lead to coronal craniosynostosis and learning disability." (PMID 31396565, 2019). "Among the four novel loci (ZIC1, PRKAR1A, AZIN1/ATP6V1C1, GLRX3), there are factors implicated in intramembranous ossification and as we show, inherent to craniosynostosis processes." (PMID 37402774, 2023). "Custom genes panel allowed us to detect novel pathogenic variants–p.Arg132* in the ERF gene (P129), and p.Ser391* in the ZIC1 gene (P131), resulting in Craniosynostosis 4 and Craniosynostosis 6, respectively." (PMID 35591945, 2022). "Also, this GWAS of skull BMD unveiled a link between bone mineralization and the pathogenesis of craniosynostosis, as illustrated by the consequences of ZIC1 disruption in zebrafish skull mineralization." (PMID 37402774, 2023). "Functional follow-up with zebrafish models provided robust evidence for the implication of PRKAR1A, ZIC1 and ATP6V1C1 in the mineralization of the skull and pointed to a conceivable role of these genes in craniosynostosis." (PMID 37402774, 2023). "We did not identify any ZIC1 copy-number changes in this craniosynostosis panel by MLPA (data not shown)." (PMID 26340333, 2015).
Dandy-Walker malformation (7 papers, 2015 to 2026). "The Fetalis test revealed the presence of a heterozygous missense mutation c.1208C > A (p.S403Y) of the ZIC1 gene, a gene possibly associated with Dandy-Walker malformation (OMIM 220200)." (PMID 27168972, 2016). "Heterozygous deletions of ZIC1 and its nearby paralog ZIC4 on chromosome 3q25.1 are associated with Dandy-Walker malformation of the cerebellum, and loss of the orthologous Zic1 gene in the mouse causes cerebellar hypoplasia and vertebral defects." (PMID 26340333, 2015). "In contrast, Zic1 and Zic4 have previously been found to control the development of glutamatergic cell types in the cerebellum and combined, heterozygous loss of function mutations of these genes have been associated with Dandy-Walker Syndrome." (PMID 37365500, 2023). "Significantly, heterozygous deletion of the homologous genes ZIC1 and ZIC4 has been shown to be involved in the Dandy-Walker malformation, a neurodevelopmental disorder characterized by hypoplasia of the cerebellar vermis and cystic dilation of the fourth ventricle." (PMID 35857265, 2022).
medulloblastoma (7 papers, 2010 to 2025). A malignant, invasive embryonal neoplasm arising from the cerebellum. "We demonstrate that ZIC1 exhibits loss-of-function (LOF) somatic events in group 4 (G4) medulloblastoma through recurrent point mutations, subchromosomal deletions and mono-allelic epigenetic repression (60% of G4 medulloblastoma)." (PMID 39753768, 2025). "Analysis of medulloblastomas in humans and mice shows that the functional consequences of ZIC1 mutations are exquisitely dependent on the cells of origin that give rise to different subgroups of medulloblastoma." (PMID 39753768, 2025). "We maintain that LOF/GOF mutations of ZIC1 are true driver events, as overexpression of ZIC1 represses malignant phenotypes in G3 medulloblastoma models while promoting malignancy in SHH medulloblastoma precursor cells, both in vitro and in vivo." (PMID 39753768, 2025). "Intriguingly, SHH medulloblastoma ZIC1 somatic mutations are found in the same 3′ region of the ZIC1 gene as previously reported germline GOF ZIC1 mutations in humans with craniosynostosis." (PMID 39753768, 2025). "As the G4 medulloblastoma ZIC1 point mutations occur in the DNA-binding domain, we conclude therefore that loss of DNA binding is at least partially responsible for the phenotype of G4 medulloblastoma ZIC1 mutants." (PMID 39753768, 2025). "To test this hypothesis, we generated ZIC1 expression constructs with mutations from G4 medulloblastoma (G4 medulloblastoma ZIC1 mutants) in the zinc finger regions or with mutations from SHH medulloblastoma (SHH medulloblastoma ZIC1 mutants) in the carboxy terminus IDR." (PMID 39753768, 2025). "Distinct ZIC1 mutations affect cells of the rhombic lip in diametrically opposed ways, suggesting that ZIC1 is a critical developmental transcriptional regulator in both the normal and transformed rhombic lip and identifying ZIC1 as an exquisitely context-dependent driver gene in medulloblastoma." (PMID 39753768, 2025). "ChIP–seq against Flag-ZIC1 demonstrates reduced DNA-binding affinity of G4 medulloblastoma ZIC1 mutant proteins, offering a mechanistic insight underlying the reduction of ZIC1 target gene induction." (PMID 39753768, 2025). "Within our 251 medulloblastoma validation cohort, three G4 tumors and two SHH tumors with ZIC1 mutations were identified." (PMID 39753768, 2025). "We noted marked overexpression after Western blotting for SHH medulloblastoma ZIC1 mutant proteins as compared to WT controls or G4 medulloblastoma ZIC1 mutant proteins." (PMID 39753768, 2025). "We determined the mono-allelic expression pattern of ZIC1/ZIC4 in a validation cohort of 251 medulloblastomas with matching RNA-seq and WGS data, assembled by combining publicly available and newly generated datasets." (PMID 39753768, 2025). "Annotating samples by ZIC1/ZIC4 allelic expression status, copy gain within SHH, copy loss within G3/G4 medulloblastoma and ZIC1 SNV status revealed that close to 20% of SHH samples harbor genetic variants promoting ZIC1/ZIC4 expression." (PMID 39753768, 2025). "On the other hand, while SHH medulloblastoma shares a direct developmental relationship with G4 medulloblastoma, ZIC1/ZIC4 events confer a GOF phenotype." (PMID 39753768, 2025). "ZIC1 ChIP–seq in GNPs transduced with ZIC1 mutant constructs also demonstrated reduced DNA-binding affinity for G4 medulloblastoma ZIC1 mutants similar to results observed in D283." (PMID 39753768, 2025). "ZIC1 events in the current cohort are found in 20% of SHH medulloblastoma and 60% of G4 medulloblastoma, making ZIC1 one of the most frequently affected driver genes in medulloblastoma biology." (PMID 39753768, 2025). "An additional possible mechanism is somatic ‘epimutation’, in which aberrant H3K27me3 marks repress ZIC1 expression, and this heritable chromatin state results in clonal expansion and eventually G4 medulloblastoma." (PMID 39753768, 2025).